HMGB1 (high mobility group box 1)
Diseases named in the same sentence as HMGB1 in open-access papers (continued):
Sharing a sentence is not in itself a finding about the gene and the disease.
Hyperglycemia (continued). "In response to the limitations of our study, our future research will build upon our current findings by investigating the effects of HMGB1 knockdown in a more complete DM phenotype that includes female mice and evaluates the therapeutic potential of targeting HMGB1 after hyperglycemia induction." (PMID 38187339, 2024). "Moreover, it is worth highlighting that our study found a nearly 34 % reduction in hyperglycemia in HMGB1 knockdown mice compared to hyperglycemia mice with fully expressed HMGB1." (PMID 38187339, 2024). "Importantly, our KEGG analysis also demonstrated that the AGE-RAGE signaling pathway was significantly perturbed in skeletal muscle following HMGB1 knockdown in hyperglycemia mice." (PMID 38187339, 2024). "In addition to evaluating glucose metabolism, we also investigated the impact of hyperglycemia reduction upon HMGB1 knockdown on the liver and kidneys, organs that play a critical role in glucose metabolism and metabolic regulation." (PMID 38187339, 2024). "As our primary focus was to investigate the impact of HMGB1 knockdown on hyperglycemia and glucose metabolism, we opted to induce only hyperglycemia without introducing obesity and dyslipidemia by only administering low-dose STZ injections over a five-day period." (PMID 38187339, 2024). "Therefore, hyperglycemia and the associated activation of AGEs-RAGE/HMGB-1 signaling observed in diabetic rats are important contributors to myocardial fibrosis." (PMID 37422477, 2023). "Elevated levels of HMGB1 are correlated both with type 2 DM and with hyperglycemia." (PMID 37373216, 2023). "It was demonstrated that hyperglycemia and insulin resistance may increase expression of both, high-mobility group box 1 protein (HMGB1) and receptors, for advanced glycation end products (RAGE)." (PMID 37373216, 2023). "Furthermore, we inhibited HMGB1 activity and observed the suppression of inflammatory factors related to hyperglycemia." (PMID 35578754, 2022). "Hyperglycemia-related cell vitality decline could be mediated by HMGB1, which was confirmed by siRNA technology." (PMID 35578754, 2022). "HMGB1 level is increased in the serum of hyperglycemic rats and the management of hyperglycemia with insulin might decrease serum HMGB1 level." (PMID 36376958, 2022). "Other studies indicated that MSC-Exo-derived miR-126 could suppress hyperglycemia-induced inflammation by down-regulating HMGB1, which can bind to TLRs and activate the NLRP3 pathway." (PMID 35047512, 2021). "In the presence of normal blood glucose levels, HMGB1 might stimulate insulin release from pancreatic beta cells, which, differently, is inhibited in the presence of hyperglycemia." (PMID 34360753, 2021). "In vitro studies have shown that in bronchial epithelial cells, hyperglycemia increases HMGB1 while it is lowered by insulin, suggesting that this protein might be a vulnerability marker besides a therapeutic target." (PMID 33912566, 2021). "Moreover, it has been previously discovered that the suppression of HMGB1 has a protective effect on hyperglycemia-induced apoptosis and mitochondrial dysfunction in cardiomyocytes." (PMID 34336950, 2021). "HMGB1 levels are related to inflammation, insulin resistance (IR), hyperglycemia, and MetS." (PMID 33912566, 2021). "Indeed, recent studies have demonstrated that HMGB1 is increased in the arterial wall of mice fed with high-fat diet or mice with hyperglycemia/hypercholesterolemia." (PMID 32211403, 2020). "An immortalized F11 DRG neuronal cell line was used to confirm whether hyperglycemia could influence the expression of HMGB1 and alter the global acetylation of H3K9 in DRG neuronal cells." (PMID 32019145, 2020). "Moreover, HMGB1 and hyperglycemia prime neutrophils for the formation of NETs (Neutrophil Extracellular Traps), complex webs of chromatin and antimicrobial proteins released by neutrophils in an attempt to contain infections." (PMID 32760352, 2020).
Hyperglycemia (continued). "Of note, hyperglycaemia may also enhance HMGB1 secretion by other types of cells such as endothelial cells, which may in turn exacerbate autoimmune progression." (PMID 32072192, 2020). "Recent evidence has shown that hyperglycemia is responsible for the hyperexpression of HMGB1." (PMID 32722545, 2020). "Our study showed that hyperglycemia results in enhanced expression of HMGB1 mRNA and protein, while BDNF overexpression inhibits the increased expression of HMGB1 in the hippocampus of diabetic mice, suggesting a possible role of HMGB1 in mediating the anti-inflammatory effects of BDNF." (PMID 31165005, 2019). "Functional studies revealed that blockade of HMGB1 may protect against hyperglycemia-induced tissue injury." (PMID 31165005, 2019). "Besides, MSC-Exos loaded with exogenous miRNA-126 were reported to alleviate hyperglycemia-induced retinal inflammation via suppressing the high-mobility group box 1 (HMGB1) signal pathway." (PMID 31470892, 2019). "Combined with above evidence, we speculate that the increased plasma HMGB-1 concentrations may largely be due to the presence of insulin resistance and the low chronic inflammation in the context of hyperglycemia." (PMID 27738641, 2016). "HMGB1 mediates hyperglycemia-induced cardiomyocyte apoptosis via ERK/Ets-1 signaling pathway." (PMID 26623724, 2016). "Interestingly, in vitro and in vivo experiments showed that hyperglycemia-induced HMGB-1 was reversed by treatment of resveratrol or metformin, both of which were considered as antioxidants." (PMID 27847406, 2016). "The expression of HMGB1 is upregulated in the kidney of diabetic rats, suggesting that the release of hyperglycemia-triggered HMGB1 may induce renal inflammatory injury." (PMID 26491232, 2015). "The apoptosis of cardiomyocytes in the HG or hyperglycaemia environment could be attenuated by knock-down of HMGB1 gene." (PMID 25210949, 2014). "This suggests that hyperglycaemia may increase the proportion of oxidized HMGB1 and HMGB1 may promote cardiomyocyte apoptosis under HG or hyperglycaemia conditions." (PMID 25210949, 2014). "With hyperglycaemia, increased HMGB1 level could promote cardiac cell death via the nuclear transcription factor Ets-1." (PMID 25210949, 2014). "In conclusion, inhibition of HMGB1 may protect against hyperglycaemia-induced cardiomyocyte apoptosis by down-regulating ERK-dependent activation of Ets-1." (PMID 25210949, 2014). "In addition, hyperglycemia-induced reactive oxygen species production increased the expression of HMGB1 and RAGE in endothelial cells." (PMID 23118492, 2012). "In addition, hyperglycemia-induced reactive oxygen species production increases the expression of HMGB1 and RAGE in endothelial cells." (PMID 21850157, 2011). "Consequently, a 34 % decrease in hyperglycemia indicate that targeting HMGB1 could potentially represent an equally effective, or even superior, therapeutic approach for managing hyperglycemia compared to existing interventions." (PMID 38187339, 2024). "Moreover, in vitro and in vivo studies of glycyrrhizin demonstrate that it improves osteogenic differentiation, attenuates lipid peroxide, restores hyperglycaemia‐induced impairment of trabecular structure and osteointegration, via inhibiting HMGB1‐RAGE cascade." (PMID 35706377, 2022). "Hyperglycemia upregulates receptor for advanced glycation end products (RAGE), a major mediator of pulmonary inflammatory responses including those in COVID-19, and RAGE ligands such as sepsis-associated HMGB1, and this activates NF-κB via a positive regulation loop." (PMID 36009285, 2022). "Thus, we examined whether miR-146a plays a role in reducing the levels of HMGB1 in REC in hyperglycemia." (PMID 26997759, 2016). "Therefore, HMGB1 is involved in hyperglycaemia-induced myocardial apoptosis in diabetic mice." (PMID 25210949, 2014). "Thus, we hypothesized that increased HMGB1 level may facilitate HG or hyperglycaemia-induced cardiomyocyte apoptosis." (PMID 25210949, 2014).
Hyperglycemia (continued). "We measured circulating levels of Cystatin C in plasma samples obtained from HMGB1 Flox TMX STZ and iHMGB1 KO TMX STZ mice 10 weeks post hyperglycemia development." (PMID 38187339, 2024). "Quantitative analysis demonstrated that iHMGB1 KO TMX STZ mice had significantly lower hyperglycemia compared to HMGB1 Flox TMX STZ mice, with a reduction of 33.99 % (p = 0.0038) eight weeks into the hyperglycemia phenotype development." (PMID 38187339, 2024). "Hyperglycemia and the resulting advanced glycated end products (AGE) and their receptor (RAGE)/High Mobility Group Box-1 (HMGB-1) molecular pathway are thought to be key players." (PMID 37422477, 2023). "Salidroside is the primary active ingredient of Rhodiola and can alleviate insulin resistance, hyperglycemia, and liver inflammation in db/db mice by inhibiting the HMGB1/RAGE/NF-κB and HMGB1/TLR4/NLRP3 signaling pathways." (PMID 37065747, 2023). "Hyperglycemia also upregulates endogenous TLR4 ligands, including the high-mobility group box 1 (HMGB1)." (PMID 37371657, 2023). "Hyperglycaemia-induced increased levels of TLR4 and HMGB1 are inhibited by the application of the Box A portion of HMGB1 and glycyrrhizin in both cultured human REC and mouse retina." (PMID 38983565, 2022). "Considering that GA was proven to be an inhibitor of HMGB1, we further explored HMGB1 expression in the sciatic nerve of rats with STZ-induced hyperglycemia." (PMID 35578754, 2022). "ZDF animals with Type 2 diabetic painful neuropathy revealed a significant increase in NLRP3, HMGB1, and TLR4 in DRG at eight weeks after hyperglycemia when compared to their control counterparts." (PMID 32019145, 2020). "In particular, inhibition of HMGB1 with HMGB1siRNA reduces ERK and Ets-1 phosphorylation induced by hyperglycemia." (PMID 31835864, 2019). "Recent studies have described that hyperglycemia increases RAGE, S100A8 and HMGB1 expression in aortic endothelial cells, both in vitro and in vivo." (PMID 28099448, 2017). "Since HMGB1 is a ligand of RAGE, the role of the RAGE axis in hyperglycemia-induced apoptosis in myocytes was investigated in the present study." (PMID 25187821, 2014). "Hyperglycaemia increased the phospho-ERK level, and inhibition of HMGB1 by shRNA significantly reduced hyperglycaemia-induced ERK phosphorylation (P < 0.05)." (PMID 25210949, 2014). "However, four weeks after inducing the hyperglycemia phenotype, iHMGB1 KO TMX STZ mice exhibited significantly lower glucose measurements (by 27.77 %, p = 0.0006) compared to HMGB1 Flox TMX STZ mice." (PMID 38187339, 2024). "Thus, hyperglycemia increases RAGE expression and HMGB1 levels, both leading to amplification of a SARS-CoV-2/HMGB1/RAGE axis." (PMID 36009285, 2022). "Although blockage of extracellular HMGB1 did not affect the systemic metabolic profiles, evidenced by hyperglycemia and glucose intolerance, glycyrrhizin rescued cardiac function and ameliorated cardiac pathological remodeling with reduced Nppb levels." (PMID 35281739, 2022). "It was reported that the HMGB1 gene contains a 3′UTR target for miR-126 and that elevated miR-126 downregulated HMGB1 and suppressed inflammatory responses of ECs during exposure to hyperglycemia." (PMID 34970357, 2021). "Beyond pathogens, metabolic factors such as hyperglycemia, Western-style diet, and endogenous molecules—including oxidized low-density lipoprotein (Ox-LDL) particles, lipoprotein(a), vimentin, and high mobility group box 1 (HMGB1)—can also induce trained immunity." (PMID 40746537, 2025). "We then proceeded to determine the most optimal method for inducing the hyperglycemia phenotype by employing three conditions: High Fat Diet (HFD), STZ administration alone with normal chow (NC + STZ), and a combination of HFD and STZ (HFD + STZ) in HMGB1 Flox Mice." (PMID 38187339, 2024).
Hyperglycemia (continued). "Six to eight weeks after hyperglycemia, ob/ob diabetic animals exhibited increased acetylation of HMGB1 in the neuronal and non-neuronal cells as compared the control group, and these mice also showed increased nuclear H3K9ac activity in non-neuronal glial cells." (PMID 32019145, 2020). "However, the role of HMGB1 in hyperglycaemia-induced apoptosis of cardiomyocytes has not been characterized." (PMID 25210949, 2014). "Our speculation was further attested as we found that blood glucose levels in iHMGB1 KO TMX STZ mice plateaued approximately four weeks after inducing the hyperglycemic phenotype, indicating that the absence of HMGB1 halted the progression of severe hyperglycemia." (PMID 38187339, 2024). "However, the signaling pathway downstream of HMGB1 that may play a role in hyperglycemia-induced synaptic impairments and neuroinflammation is not yet clear." (PMID 31165005, 2019).
systemic lupus erythematosus (99 papers, 2009 to 2026). An autoimmune multi-organ disease typically associated with vasculopathy and autoantibody production. "HMGB1–DNA complexes, for example, have been implicated in the pathogenesis of systemic lupus erythematosus." (PMID 29543735, 2018). "High-mobility group box 1 (HMGB1), an intracellular alarmin that is capable of inducing the formation of antinuclear autoantibodies and causes lupus-like conditions in mice, is identified as a novel potential target by bioinformatics analysis." (PMID 27648302, 2016). "Similarly, serum and urine HMGB1 levels have been found to be associated with disease activity and renal involvement in patients with systemic lupus erythematosus." (PMID 38481996, 2024). "In autoimmune diseases such as systemic lupus erythematosus (SLE), the level of HMGB1 is significantly elevated and is closely associated with the pathological process of the disease." (PMID 40969278, 2025). "While preclinical models of lupus and atopic dermatitis have shown the efficacy of HMGB1 blockade, dermatology-specific clinical trials are still lacking." (PMID 40308590, 2025). "Certain ANAs, like antibodies against a nuclear DNA-binding protein (HMGB1), decreased albuminuria, complement deposition, and neutrophil recruitment in a murine lupus model." (PMID 37550754, 2023). "Elastase induced AAA shared five top autophagic SG pathways with that of Ang-II induced AAA, namely, cardiac hypertrophy, systemic lupus erythematosus in B cell signaling, neuroinflammation signaling, HMGB1 signaling, and IL-17 signaling." (PMID 35320939, 2022). "Autophagy SGs at the day 7 AAA aortas had five functional pathways, namely, neuroinflammation signaling, HMGB1 signaling, IL-17 signaling, systemic lupus erythematosus in B cell signaling, cardiac hypertrophy signaling." (PMID 35320939, 2022). "The erythropoietin signaling pathway is significantly upregulated in CM-positive human and mouse plasma, whereas HMGB1, IL-17, and systemic lupus erythematosus in B-cell signaling pathways were significantly downregulated in CM-positive plasma of both species." (PMID 35073748, 2022). "In contrast, western blot assessment demonstrated huge differences between healthy controls and patients with active lupus, who expressed high HMGB1 levels." (PMID 34943830, 2021). "Like lupus, circulating HMGB1 levels have been reported to be increased and closely associated with the disease activity of AAV." (PMID 33807604, 2021). "Another study unexpectedly found that lupus patients with active disease had HMGB1 levels measured by ELISA to be at the same or even at lower levels than in healthy controls." (PMID 34943830, 2021). "Treatment with m2G7 did not affect lupus nephritis in MRL/lpr mice, despite the fact that systemic levels of HMGB1 are increased in lupus." (PMID 32265930, 2020). "Successful therapeutic outcome has in contrast been reported in another mouse lupus model using a different anti-HMGB1 mAb." (PMID 32265930, 2020). "Since then, a number of studies have confirmed that HMGB1 plays a central role in the pathogenesis of many diseases, including systemic lupus erythematosus (SLE), acute liver failure (ALF), tumors, and cerebrovascular diseases." (PMID 31001089, 2019). "We evaluated the efficacy of a neutralizing anti-high mobility group box 1 (HMGB1) monoclonal antibody in MRL/lpr lupus-prone mice." (PMID 28649578, 2017). "Type 1 IFN is known as a crucial cytokine in lupus;11 therefore, these data suggest that HMGB1 is involved in lupus pathogenesis." (PMID 28649578, 2017). "Studies in animal models of arthritis and lupus have shown that treatment with anti-HMGB1 antibodies can strikingly attenuate disease by blocking the pro-inflammatory function of HMGB1." (PMID 26596890, 2015).